VWF (von Willebrand factor)
Diseases named in the same sentence as VWF in open-access papers (continued):
Sharing a sentence is not in itself a finding about the gene and the disease.
Thromboembolism (29 papers, 2011 to 2025). The formation of a blood clot inside a blood vessel that subsequently travels through the blood stream from the site where it formed to another location in the body, generally leading to vascular occlusion at the distant site. "An increased level of vWF in the blood has been linked to a greater likelihood of thromboembolism and cardiovascular problems." (PMID 38397876, 2024). "The association between ABO blood type and bleeding risk and thromboembolic diseases is influenced primarily by the plasma levels and biologic activity of the Von Willebrand factor (VWF) and glycosyltransferase activity." (PMID 37568521, 2023). "A clinical study pointed out that ADAMTS13 can regulate the VWF thrombogenic activity, causing thromboembolism in AF." (PMID 34276770, 2021). "The link between the ABO blood type and thromboembolic diseases and bleeding risk is intervened by the glycosyltransferase activity and plasma levels, and the biologic activity of Von Willebrand factor, a carrier protein for coagulation factor VII which is low in the blood group 0." (PMID 37568521, 2023). "In addition, high FVIII, von Willebrand Factor, and fibrinogen is associated with an increased risk of (recurrent) thromboembolism,39, 40, 41, 42highlighting the need for increased anticoagulant therapy." (PMID 33235946, 2020). "Our findings clearly demonstrate that the rs495828/rs2519093 polymorphism in ABO gene represent an independent risk factor in PNH patients for thromboembolism, the mechanism for the associations probably involved in the regulation of plasma level of vWF and factor VIII." (PMID 29190926, 2017). "Among patients with NVAF, those who experience complications related to thromboembolism (TE) have higher activity levels and concentrations of vWF antigen." (PMID 38397876, 2024). "In conclusion, individuals with group O are at lower risk for thromboembolism because they have lower plasma FVIII and vWF levels, but are at higher risk of bleeding than group A individuals." (PMID 35735664, 2022). "Patients with PPCM already face an increased risk of thromboembolism because of the procoagulant activity postpartum due to the elevation of factors VII, X, VIII, fibrinogen, and von Willebrand factor." (PMID 21608428, 2011). "Additionally, this paper noted an elevated level in blood-clotting factors such as tissue factor, factor VII, and Von Willebrand Factor (VWF), placing these patients at a greater risk of forming thromboembolisms and microthrombi." (PMID 41157587, 2025). "Histological clot classification and identification of functional molecules and blood cells (vWF, fibrin, platelets, leukocytes, and PLAs) are important to gain mechanistic insights into thrombus formation of thromboembolic diseases like acute ischemic stroke or during ECMO therapy." (PMID 38962744, 2024). "Reduced ADAMTS13 activity may result in an accumulation of ultra-large VWF on endothelial surface and heightened platelet adhesion and aggregation, promoting thromboembolism and metastasis." (PMID 29152610, 2017). "Therefore, patients who came back for follow-up were tested for the plasma levels of vWF and factor VIII, the risk factors associated with thromboembolism and the possible underlying mechanism was also investigated in this study." (PMID 29190926, 2017). "Yet, the proactive screening of VWF levels on a regular basis to assess the risk of thromboembolic disease in individual patients has still not been recommended by medical societies." (PMID 24937073, 2014). "It is considered that elevated levels of vWF, FVIII, and fibrinogen, along with reduced fibrinolytic activity and decreased levels of plasminogen, contribute to the presence of a hypercoagulable state and a predisposition to thromboembolism and vascular diseases in patients with hyperthyroidis." (PMID 38541980, 2024).
Thromboembolism (continued). "D-dimer, platelet counts, IPF, and vWF as well as TEG can be used to predict thrombotic events, to determine the prognosis of thromboembolism, and to measure the success of therapy." (PMID 37092518, 2023). "Unlike the HM2, TORVAD caused minimal VWF degradation and hemolysis and did not activate platelets in an ex vivo study, and sheep implanted with TORVAD showed similar findings with no thromboembolism despite lack of anticoagulation." (PMID 36979735, 2023). "Increase of peripheral vWF and IL6 levels after procedure supports current AF ablation management with careful control of post-procedural anticoagulation to avoid ablation-related thromboembolism." (PMID 25390649, 2014).
acute coronary syndrome (28 papers, 2009 to 2025). Signs and symptoms related to acute ischemia of the myocardium secondary to coronary artery disease. "VWF appears to be a strong indicator of cardiovascular risk, and patients with acute coronary syndrome (ACS) have elevated VWF levels in their plasma." (PMID 36684571, 2022). "Higher level of vWF is a risk factor in acute coronary syndromes, and patients with vWF deficiency show resistance to thrombosis." (PMID 33121005, 2020). "The immediate rise in VWF in acute coronary syndrome (ACS) is associated with adverse outcomes." (PMID 32095288, 2020). "Von Willebrand factor (VWF) is an emerging risk factor in acute coronary syndromes." (PMID 24453831, 2013). "PFA-100 may be a useful tool to risk stratification in acute coronary syndromes given its sensitivity to VWF." (PMID 24453831, 2013). "VWF typically rises during an acute coronary syndrome, and the extent of this VWF release is an independent predictor of adverse clinical outcomes in these patients." (PMID 36984822, 2023). "VWF is an acute phase protein response to vascular injury and has been reported in several diseases such as acute coronary syndrome, cancer, and TBI." (PMID 35928129, 2022). "Plasma VWF levels follow a typical time course during acute coronary syndrome, where they are elevated at 24 h and peak at 48 to 72 h." (PMID 36613770, 2022). "Accumulation of VWF in subendothelial matrix in our study is consistent with Dox induced vascular damage since elevated levels of VWF were reported during the course of acute coronary syndrome or thromboembolyic cardiovascular events." (PMID 21829519, 2011). "Both vWF and IL-6 are released into the plasma during acute coronary syndromes and are predictive of adverse outcomes." (PMID 20822968, 2010). "Increasing evidence suggests a potential mechanistic role for vWF in the pathogenesis of acute coronary syndromes." (PMID 19958549, 2009). "Concerning miR-143 and miR-145, their downregulation has been associated with the upregulation of the VWF protein in patients with acute coronary syndrome and of the VWF transcript during the endothelial differentiation of human adipose-derived stem cells (hADSCs)." (PMID 37762470, 2023). "In acute coronary syndrome (ACS), rapid rises in VWF are associated with poor outcome." (PMID 36684571, 2022). "Moreover, the extent of vWF release in patients with acute coronary syndrome was an independent predictor of adverse clinical outcome." (PMID 30762155, 2019). "Moreover, the very good negative predictive value of a CEPI-CT >190 sec in ruling out VWF ≥75° percentile makes PFA-100 a reasonable and reproducible test in thrombotic risk stratification after acute coronary syndromes." (PMID 24453831, 2013). "Since almost all acute coronary syndromes (ACSs) result from thrombus formation in preexisting atherosclerosis, and given the key role of vWf in arterial thrombus formation, this biomarker attracted considerable interest as a predictor of cardiovascular disease (CVD)." (PMID 21904649, 2011). "The aptamer ARC1779 (49-nt long conjugated with PEG) binds to the A1 domain of the von Willebrand factor (VWF), for use in the acute coronary syndromes." (PMID 32659966, 2020). "Independent of plaque burden, high VWF levels are predictive of adverse cardiovascular outcome and death during one-year follow-up in acute coronary syndrome and stable angina pectoris patients." (PMID 36553147, 2022).
anemia (27 papers, 2005 to 2026). A reduction in the number of red blood cells, the amount of hemoglobin, and/or the volume of packed red blood cells. "In iron deficiency anemia, reduced hemoglobin availability and microcytosis disturb blood rheology, leading to shear stress–induced release of von Willebrand factor (vWF) from endothelial cells." (PMID 41497120, 2026). "While VWF variants are well-known to result in clotting disorders, this gene is only circuitously related to anemia (i.e., prolonged/heavy bleeding from the thrombopathia can result in an iron-deficiency anemia); since “anemia” was a search term, this is likely driving the VarElect score for VWF." (PMID 41300811, 2025). "Anemia is associated with a bleeding tendency, but on the other hand iron-deficiency anemia is known to predispose individuals to thrombosis via hypoxia and distal endothelial activation and release of von Willebrand factor and FVIII." (PMID 39624963, 2024). "In iron deficiency anemia, elevated platelet counts and MPV can signal increased thrombotic risk, while in hemolytic anemias, D-dimer, vWF, and NETosis markers identify children at heightened risk for stroke or venous thromboembolism." (PMID 41497120, 2026). "This hematological recovery pattern mirrors pathophysiological mechanisms observed in Heyde's syndrome, where high-gradient aortic stenosis induces von Willebrand factor abnormalities and subsequent gastrointestinal angiodysplasia-related anemia." (PMID 41445866, 2025). "Increased bleeding is believed to be primarily caused by platelet dysfunction, with minor contributions coming from anemia’s aftereffects, changes in the coagulation cascade—including aberrant vWF and platelet interactions—elevated nitric oxide and impaired fibrinolysis." (PMID 37834890, 2023). "Proposed mechanisms include platelet storage pool deficiency, abnormal platelet metabolism, endothelial cell changes, increased cyclic adenosine monophosphate (cAMP), abnormal platelet binding to von Willebrand factor (vWF), effects of anemia, and fibrinogen impairment." (PMID 23878808, 2013). "They had more D-dimers (p = 0.005), a lower ADAMTS13 activity (p = 0.002) with higher vWF:Ag/ADAMTS13 activity ratios (p = 0.005), higher CRP levels (p < 0.001) and more anemia (p = 0.02)." (PMID 38915768, 2024). "Anemia leads to the worsening of organ failure, as hypoxia results in enhanced release of FVIII and VWF." (PMID 37210074, 2023). "Although the pathogenetic model of TTP in both congenital and acquired cases is the diminished VWF cleavage, difficulties in the measurement of ADAMTS13 antigen and antibody, usually lead to a clinical diagnosis based on laboratory findings consistent with microangiopathitic anemia." (PMID 28791286, 2017).
type 2 diabetes (26 papers, 2011 to 2025). "In a subset of type 2 diabetes patients, we have indeed shown that the setting characterized by VWF-bound carbonyls >50 pmol/mg is significantly associated with micro- and macro-angiopathies." (PMID 23383177, 2013). "In this study, we examined whether ADAMTS13 activity or VWF antigen levels are associated with risk of type 2 diabetes in a large prospective population-based cohort study." (PMID 27787621, 2017). "This study was aimed at assessing in patients with type 1 and type 2 diabetes whether protein carbonyls, marker of oxidative stress, are associated with both the level and oxidation status of VWF as well as with micro- and macroangiopathic complications." (PMID 23383177, 2013). "Notably, in the Munich General Practitioner Project and in the ARIC study, increased levels of VWF:ag were identified as risk factors for macrovascular prevalence and mortality in type 2 diabetes." (PMID 23383177, 2013). "Particularly in type 2 diabetes and prediabetes, vWF plays a dominant role in the development of cardiovascular disease and is closely associated with increased CVD risk and all-cause mortality in this population." (PMID 39175055, 2024). "Moreover, vWF was reported as a prognostic marker for cardiovascular complications in type 2 diabetes patients, as indicated by another systematic review and meta-analysis." (PMID 40283058, 2025). "We found that the genetically determined von Willebrand factor (VWF) levels may increase the risk of CAD and type 2 diabetes (T2D) (P < 8.4 × 10−6, i.e., 0.05/5952 computed by 64 proteins and 93 traits)." (PMID 36797296, 2023). "In conclusion, increased serum HIF-1α, VEGF, vWf, and IGF-1 and decreased serum 25(OH)VD3 may have an association with diabetic renal damage in type 2 diabetes patients." (PMID 27069929, 2016). "In particular, increased ET-1 and VWF levels were found in type 1 and type 2 diabetes patients." (PMID 23383177, 2013). "We previously showed that type 2 diabetes patients have higher ADAMTS13 activity compared with controls, which is inconsistent with a mechanism involving VWF’s prothrombotic function." (PMID 27787621, 2017). "Significant reductions in the majority of these cytokines, such as hsCRP, MCP-1, vWF%, fibrinogen and E-selectin were observed in the TZD group compared with those of the placebo group among patients with type 2 diabetes." (PMID 25897968, 2015). "Several studies have shown that circulating levels of ICAM-1, E-selectin, tPA:Ag, vWF:Ag, and PAI-1:Ag have been linked to the risk of type 2 diabetes in populations without the previous history of GDM." (PMID 22577379, 2012). "These include NOX-E36 L-RNA aptamer against CCL2 ligand in Type 2 diabetes, G-quadruplex forming AS1411 DNA aptamer against nucleolin in acute myeloid leukemia, and phosphorothioate-modified ARC1779 DNA aptamer against von Willebrand factor (vWF) in carotid artery disease." (PMID 22359573, 2012). "Thus the very high levels of VWF and propeptide seen here might be markers of severe pathology (e.g. coma) with malaria infection rather than specifically cerebral malaria." (PMID 22125593, 2011).
Hyperglycemia (25 papers, 2016 to 2026). An increased concentration of glucose in the blood. "Distribution patterns of blood vessel-bound factors of VWF and eNOS in the current study were used to confirm that the status of vascular disturbances caused by hyperglycemia could be overcome with SOE treatment." (PMID 35966750, 2022). "A potential underlying mechanism for platelet hyperactivity in hyperglycemia could be an upregulated expression of pro-aggregatory factors like P-selectin, thromboxane A2 and von Willebrand factor (vWF) antigen, amplifying the aggregation and adhesion of platelets." (PMID 34072487, 2021). "Previous studies have identified that hyperglycemia suppresses microRNA-24 and regulates VWF secretion." (PMID 40625905, 2025). "VWF, upregulated in endothelial cells due to oxidative stress from hyperglycemia, is critical in this process, making it a potential target for managing hyperglycemia-induced tumor metastasis." (PMID 38394492, 2024). "During hyperglycaemia, ROS produced by AR can accelerate thrombus formation in diabetic vessels by activating c-Myc, inhibiting miRNA-24 and enhancing von Willebrand factor (VWF) release from endothelial cells in diabetic patients." (PMID 37660030, 2023). "Hyperglycemia in type 2 diabetic patients (abnormal glycemic clamp technique) was associated with increased activity of thromboxane A2 (TXA2) and von Willebrand factor." (PMID 34912898, 2021). "Hyperglycemia may lead to abnormal endothelial function in patients with DM, resulting in increased vWF antigen and activity." (PMID 37746066, 2023). "Intrauterine hyperglycemia may be associated with impaired endothelial function assessed by APV by fetal echocardiography and vWF levels a biomarker of endothelial function." (PMID 34777257, 2021). "Moreover, hyperglycemia stimulates the production of coagulation factors such as von Willebrand factor, factor VII, factor VIII, factor IX, factor XII, the extrinsic pathway, and thrombin factor, which leads to excessive thrombus formation in the arteries, veins, and microvascular circulation." (PMID 33585030, 2021). "On the other side, acute, short-term hyperglycaemia has been proposed to produce transient increased platelet activation after exposure to high shear stress both in vitro and in vivo in diabetic patients, possibly involving enhanced levels of Von Willebrand factor." (PMID 31706305, 2019). "To study the impact of hyperglycemia and aging on HUVEC tubule function, we added another marker of vascular injury, vWF, ICAM-1, and performed tubular studies." (PMID 38540749, 2024). "This study is the first to demonstrate, in a diabetic rat model, the distribution and hyperglycemia-induced changes in the expression of MR, HSD11β2, VEGF, vWF, and ZO-1 in specific skin structures, including blood vessels, the epidermis, hair follicles, and sebaceous glands." (PMID 41511372, 2026). "In keeping, another independent determinant of vWF was HbA1c, a marker of abnormal glycation of circulating proteins in response to hyperglycaemia, whereas no independent impact of insulin resistance was observed." (PMID 36313186, 2022).
angiosarcoma (22 papers, 2007 to 2025). A malignant tumor arising from the endothelial cells of the blood vessels. "The loss of vWF has also been reported in human angiosarcomas and canine HSA cell lines and occurs in undifferentiated malignant ECs." (PMID 22839755, 2012). "Immunohistochemical markers such as vimentin, CD31, and von Willebrand factor are used to diagnose vascular hamartomas, hemangioma and hemangiosarcoma." (PMID 38895709, 2024). "High VWF:Ag was also found two dogs with active hemorrhage: one dog with Scott syndrome and severe epistaxis and one dog with hemangiosarcoma and hemoabdomen." (PMID 32582782, 2020). "The cells stain for vascular markers such as CD 31 (90% angiosarcomas), CD34 (50% of angiosarcoma), and less often with von Willebrand factor and occasionally show cytokeratin immunoreactivity." (PMID 23198186, 2012). "Although von Willebrand factor is the most specific of the vascular markers, it is also the least sensitive, often present in a few angiosarcomas as weak focal staining." (PMID 20179806, 2010). "Angiosarcomas express (to a greater or lesser degree) the usual vascular antigens, including von Willebrand factor, CD31, and CD34." (PMID 20179806, 2010). "In some other studies hepatic and splenic sonography or platelet level was used to assess this effect and the VWF was used for the early detection of angiosarcoma." (PMID 17686177, 2007). "Spindle cells in angiosarcoma express endothelium markers such as CD31, CD34, and the von Willebrand factor antigen." (PMID 41488269, 2025). "Histologically, angiosarcoma is characterized by polygonal, rounded, spindled endothelial cells with immunochemical analysis positive for CD31, CD34, von Willebrand factor, and vascular endothelial growth factor (VEGF)." (PMID 40125238, 2025). "On immunohistochemical analysis, the angiosarcoma component expresses endothelial markers CD31, CD34 and, less extensively, von Willebrand factor (factor VIII)." (PMID 25487416, 2014). "In the case of reduced or absent CD31 immunoreactivity in a suspected hemangiosarcoma, additional immunohistochemistry can be performed, including von Willebrand factor, vascular endothelial growth factor A, or angiopoietin-2." (PMID 37104402, 2023). "In contrast to an angiosarcoma, the cells of ASCC are negative for endothelial markers such as CD31, CD34 and von Willebrand factor and these markers must be included in differentiating ASCC from angiosarcoma." (PMID 21223553, 2011).